LEP (leptin)
Diseases named in the same sentence as LEP in open-access papers (continued):
Sharing a sentence is not in itself a finding about the gene and the disease.
Obesity (continued). "Leptin gene therapy is expected to become an effective treatment option for obesity and diabetes." (PMID 39897330, 2025). "Mutations in LEP or LEPR lead to severe, early-onset obesity." (PMID 41150735, 2025). "In 77 Polish children with obesity, the LEP concentration was 40.5 ng/mL." (PMID 40586327, 2025). "However, despite this compensatory activation, obesity still develops, likely because downstream signalling is impaired by leptin resistance or synaptic dysfunction induced by chronic HFD exposure." (PMID 41366139, 2025). "Obesity can contribute to CKD through multiple mechanisms including volume expansion (leading to glomerular hyperfiltration) and the effect of adipocytokines (leptin and aldosterone) to cause renal injury and fibrosis." (PMID 39551891, 2025). "Emerging evidence highlights the dysregulation of adipokine homeostasis—particularly reduced adiponectin and elevated leptin levels in obesity—as critical mediators of thyroid cancer pathogenesis through dual modulation of cellular proliferation, apoptosis, invasiveness, and angiogenesis." (PMID 40620232, 2025). "The increased olfactory bulb volume observed in individuals with obesity may be related to neuronal plasticity induced by alterations in metabolic hormones such as leptin and insulin." (PMID 40868460, 2025). "Moreover, high-H relatives showed increased levels of obesity-related metabolic hormones, including leptin, PAI-1, and active amylin, both positively correlated with HOMA-IR (with only a trend observed for PAI-1)." (PMID 39656436, 2025). "In addition, the results suggested that skeletal muscle was the most notable site of action of SFN, whose peripheral action of Nrf2 signals alleviates leptin resistance and suppresses fatty acid synthesis, leading to protection against obesity." (PMID 39940284, 2025). "However, elevated plasma leptin levels in individuals with overweight or obesity, together with leptin resistance as a major contributor to obesity pathogenesis, indicate altered leptin expression in obesity." (PMID 40620794, 2025). "However, there is a lack of reports that directly compare the effects of commonly used animal fat sources on the development of diet-induced obesity and leptin resistance." (PMID 40690443, 2025). "Therefore, in the context of human obesity, although serum levels of leptin are typically elevated, there is a diminishment in the endocrine and paracrine effects of leptin due to leptin resistance at the leptin receptor, analogous to obesity-related IR." (PMID 39997710, 2025). "Hormonal signaling via leptin, insulin, and ghrelin receptors in the olfactory bulb and mucosa also influences odor detection and processing, and such hormonal imbalances are common in obesity." (PMID 41010291, 2025). "Leptin, in particular, is implicated in the upregulation of inflammatory cytokines such as IL-6 and TNF-α, contributing to the low-grade inflammation characteristics of obesity." (PMID 39857920, 2025). "Indeed, since leptin secretion is proportional to the extent of AT and, in turn, leptin increases tumor growth and invasiveness in different cancer types, including renal cancer, elevated incidence of obesity parallels higher risks of kidney cancer deaths." (PMID 39806854, 2025). "Furthermore, while the role of LEP in obesity is well established, this study provides new evidence linking the BioLEP/LEP ratio more closely to lipid metabolism, suggesting its potential as a biomarker for metabolic risk in SO." (PMID 40586327, 2025). "In this present study, the leptin levels in those with comorbid asthma and obesity/overweight were substantially higher than in children with obesity/overweight alone, while leptin expression in children with obesity/overweight alone was higher than in children with asthma alone." (PMID 40083433, 2025).
Obesity (continued). "Chronic activation of these neurons caused massive obesity, and importantly, the observed obesity is associated with normal p-STAT3-mediated leptin signaling but resistant to leptin treatment, highlighting a dissociation between cellular leptin sensitivity and phenotypic leptin resistance." (PMID 40540394, 2025). "Improvement of leptin sensitivity can, however, not fully explain protection from obesity in Gipr deficient mice, since lack of GIPR decreases body weight in obese leptin deficient ob/ob mice." (PMID 40024571, 2025). "The impact of leptin on the SM in human obesity remains incompletely understood." (PMID 39997710, 2025). "Building on this framework, a number of authors have proposed that leptin resistance may provide a mechanistic link between obesity, metabolic dysfunction, and depressive symptomatology." (PMID 40507778, 2025). "Furthermore, fatty acid‐induced leptin resistance is also involved in the diet‐induced obesity process." (PMID 41292674, 2025). "Obesity also induces a chronic pro-inflammatory state driven by altered adipokine secretion, specifically increased leptin and decreased adiponectin, which promotes oxidative stress, DNA damage, and the activation of carcinogenic pathways, collectively promoting tumor progression." (PMID 41432903, 2025). "Such “central leptin resistance” combined with reactive peripheral upregulation may be one reason that in obesity, peripheral leptin is unable to exert neuroprotection and may even promote neuroinflammation." (PMID 41516046, 2025). "For example, BMAT upregulates the expression of leptin, a pro-inflammatory adipokine that modulates immune responses, and promotes the recruitment of Ly6Chigh monocytes, which contribute to systemic inflammation and insulin resistance during obesity." (PMID 40852589, 2025). "Moreover, adiponectin and leptin have been shown to have a close interaction in obesity pathology and related metabolic complications." (PMID 39812542, 2025). "The biological mechanisms behind obesity‐induced depressive comorbidities are not fully understood but may involve inflammation, neuroimmunity, the hypothalamic–pituitary–adrenal axis, and leptin regulation." (PMID 41292674, 2025). "Overall, the increased excitatory glutamate and aspartate neurotransmitters may be responsible for the damage of the hypothalamic nuclei under the effect of leptin resistance and may lead to overeating, thus exaggerating obesity and its complications." (PMID 41309900, 2025). "However, in obesity and chronic inflammation, hyperleptinemia and leptin resistance are frequently observed." (PMID 40095687, 2025). "Furthermore, androgen‐dependent organs such as the prostate are also affected by the triad of obesity, hyperleptinemia, and suppressed leptin signaling." (PMID 40195898, 2025). "Evidence on whether leptin replacement is effective when extreme obesity develops in the ob/ob mice remains scarce." (PMID 40709262, 2025). "In a state of extreme obesity, leptin resistance—characterized by impaired hypothalamic signaling, neuroinflammation, and receptor desensitization—may reduce the ability of exogenous leptin to enhance fat metabolism." (PMID 40192745, 2025). "Moreover, the antagonistic effect of lipocalin on leptin signaling is diminished in the context of obesity, thereby exacerbating the progression of OA." (PMID 40964689, 2025). "For example, targeting leptin resistance or VEGF pathways could potentially improve some of the complications associated with GDM and obesity." (PMID 41302116, 2025). "However, leptin is produced proportionally to body fat, and studies have indicated that individuals with obesity have hypothalamic resistance to its action." (PMID 41572970, 2025). "More recently, SFN was shown to reduce obesity by reversing leptin resistance." (PMID 39940284, 2025).
Obesity (continued). "This is particularly relevant in patients with obesity, type 2 diabetes, or metabolic syndrome, where dysregulated leptin pathways and impaired β3 signaling may influence clinical outcomes." (PMID 41463309, 2025). "However, in obesity, leptin resistance develops, leading to impaired hypothalamic signaling and persistent hyperphagia." (PMID 40792318, 2025). "One possible explanation is that the adipose tissue itself leads to a systemic pro-inflammatory state by promoting the secretion and release of pro-inflammatory mediators such as IL-6, IL-1β, TNF-α, leptin, and MCP-1, so that obesity per se is a risk factor for the development of EDy." (PMID 40005022, 2025). "Additionally, they observed that leptin and obesity were inversely and significantly correlated (p ≤ 0.05) with FVC and FEV1." (PMID 40870537, 2025). "This may be clarified by higher leptin levels in obesity that accelerate skeletal and dental growth, whereas pro-inflammatory adipokines further exaggerate these changes." (PMID 40682059, 2025). "This suggests that leptin may not only be relevant in the context of obesity but may also serve as a marker for other inflammation-related processes implicated in the pathophysiology of depression." (PMID 40507778, 2025). "However, elevated adiponectin in established AD has also been reported, suggesting a compensatory increase or “adiponectin resistance” where receptor signaling is impaired despite ligand abundance, mirroring patterns seen with leptin in obesity." (PMID 41155642, 2025). "Additionally, obesity often leads to leptin resistance, disrupting signalling and regulatory mechanisms and negatively affecting cognitive function." (PMID 39949539, 2025). "Maternal caloric restriction during pregnancy blunts the leptin neonatal surge, which impairs axon development from ARC POMC and AGRP/NPY neurons and leads to adulthood outcomes linked to vulnerability to obesity." (PMID 40474775, 2025). "Leptin, an adipocytokine predominantly secreted by adipose tissue, is best known for regulating appetite and energy balance, with circulating concentrations rising markedly in obesity." (PMID 41470134, 2025). "Additionally, genetically obese mouse models, such as ob/ob or db/db mice, have been utilized in combination with CRC models to investigate the role of obesity-related genes, particularly those involved in the leptin signaling pathway, in tumorigenesis." (PMID 40406485, 2025). "Additionally, reduced physical activity, leptin resistance, and diminished growth hormone secretion in individuals with obesity further destabilize the equilibrium between muscle synthesis and catabolism." (PMID 40607039, 2025). "VAT overproduces leptin in obesity, activating its receptor on CRC cells." (PMID 40599844, 2025). "Stevia significantly improved leptin and ghrelin receptor mRNA expression, glucose levels, and insulin resistance in obese rats, showing its potential as an effective dietary intervention for managing obesity." (PMID 40087612, 2025). "Although rare monogenic obesity syndromes (e.g., those caused by mutations in the LEP gene, leptin receptor gene (LEPR), melacortin 4 receptor (MC4R), and fat mass and obesity-associated gene (FTO)) provide valuable information about the pathways regulating body weight." (PMID 41150735, 2025). "Augmented levels of leptin and decreased levels of peptide tyrosine tyrosine are features of peripheral IR in obesity, and similar abnormalities in AD brains reveal that peptide tyrosine tyrosine and leptin levels could also be markers of brain IR." (PMID 40379890, 2025). "In vivo investigation of leptin sensitivity may be particularly important for providing evidence of the metabolic and cognitive effects necessary for developing novel anti-obesity treatments." (PMID 40607230, 2025). "However, obesity commonly leads to leptin resistance, characterized by diminished cellular responsiveness despite elevated circulating levels." (PMID 41002965, 2025).
Obesity (continued). "Notably, leptin serves as a critical nexus between metabolic dysfunction and immune activation in obesity, with its pro-inflammatory effects spanning both innate and adaptive immunity." (PMID 40699756, 2025). "However, chronic exposure to elevated leptin, as seen in obesity or aging, has been shown to suppress CSR-related molecules." (PMID 41516046, 2025). "Individuals with obesity have been reported to exhibit high circulating leptin concentrations." (PMID 41515130, 2025). "In the context of leptin resistance, which is commonly observed in metabolic syndromes such as obesity and type 2 diabetes, macrophages may exhibit a dysregulated response." (PMID 40095902, 2025). "The endocrine dysregulation observed in children with obesity, including insulin resistance, thyroid dysfunction, altered reproductive development, and hormonal imbalances like leptin resistance and cortisol dysregulation, underscores the urgent need for targeted interventions." (PMID 40370785, 2025). "Exaggerated nutrient-stimulated GIP secretion is also observed in obese leptin-deficient ob/ob mice and in humans with obesity [481,], but this has not been confirmed by other studies [492,]." (PMID 40024571, 2025). "Leptin, an indicator of subcutaneous fat stores and thus elevated in individuals with obesity, rises gradually during the peripubertal period and signals when energy stores are sufficient for initiation of puberty, but it cannot alone trigger the onset of puberty." (PMID 41291865, 2025). "Dysregulation of leptin and insulin signaling pathways within brain regions may contribute not only to the development of obesity, but also systemically affect the peripheral organs, thereby manifesting as metabolic diseases involving altered DNA methylation." (PMID 40195216, 2025). "The plasma level of LEP was also found to correlate with age among children with obesity in Italy." (PMID 40586327, 2025). "The attenuation of the relationship between CAMKK1 and leptin in individuals with obesity may also suggest that other metabolic factors may be involved in leptin‐binding cascades." (PMID 40965347, 2025). "Neuronal deficiency of LGR4 improves hypothalamic leptin sensitivity via suppression of β- catenin signaling, which subsequently increases energy expenditure and decreases food intake, thus rendering mice resistant to high fat diet (HFD)-induced obesity." (PMID 40069508, 2025). "This relationship suggests that excessive leptin released from AT may promote IL-36 signalling in tumour cells, linking obesity with amplified inflammatory responses that could facilitate cancer progression." (PMID 40268791, 2025). "The positive association between CAMKK1 and leptin was attenuated in individuals with obesity in comparison to controls, but no similar effect was detected in patients with T2DM." (PMID 40965347, 2025). "In individuals with obesity, the level of leptin in blood serum is higher than that in those with a lower body mass index (BMI), which can promote cancer cell proliferation, invasion, and metastasis through various signaling pathways similar to the ones discussed in previous sections." (PMID 40722646, 2025). "Secondly, the relationships between most of the variables collected in this report including obesity, PA, gait stability, and leptin are complex and subject to modification by many other confounders, such as the use of supplements and/or medications, sleep quality, and mental health status." (PMID 40001498, 2025). "Moreover, maternal leptin positively correlated with BMI at delivery in the GDM pregnancies, suggesting that the interplay between maternal obesity and leptin influences the infant cord blood leptin and birthweight." (PMID 40045330, 2025). "Regardless of obesity degree, leptin, adiponectin, and the L/A ratio were strongly associated with insulin resistance and cardiometabolic risks, with the L/A ratio demonstrating the strongest associations." (PMID 39857920, 2025).
Obesity (continued). "Our finding that Faecalbaculum rodentium was inversely correlated with both plasma leptin and adiposity suggests that it may play a role in reducing obesity." (PMID 40048260, 2025). "English-language publications were included by searching the database - PubMed, ScienceDirect, EMBASE, using the terms - adolescent girls, PCOS, adipokines, leptin, adiponectin, resistin, apelin, vaspin, visfatin, ghrelin, omentin, obesity, insulin resistance, metabolic syndrome." (PMID 40491594, 2025). "Therefore, potential effects of CCJ12 on various obesity-related risk factors (bodyweight, cholesterol, HDL, LDL, and triglycerides, leptin, adiponectin, sE-selectin, CRP, MCP-1 and TNF-alpha) were studied in rats fed a high fat diet." (PMID 40770283, 2025). "In another study, high levels of IFN-γ were associated with high levels of leptin in asthmatic children with obesity, but not in asthmatic children with normal weight." (PMID 41153538, 2025). "Although leptin is a key regulator of food intake and energy homeostasis, its therapeutic efficacy in obesity is limited in part by leptin resistance—a condition characterized by elevated leptin levels and reduced leptin sensitivity during times of nutritional abundance." (PMID 41016636, 2025). "Thus, high levels of leptin maintain inflammation in Pso, integrating obesity-related mechanisms with immune cell activity and the progression of autoimmunity." (PMID 40893809, 2025). "Furthermore, elevated hypothalamic expression of FTO and CX3CL1, coupled with increased levels of the cytokine signaling suppressor SOCS3, disrupts leptin signaling, promoting leptin resistance and obesity." (PMID 41007727, 2025). "Another important feature of stress-related obesity is the rise in circulating ghrelin following stress, which further drives comfort-food consumption, along with reducing leptin levels after stress—particularly pronounced in women—potentially impairing appetite suppression." (PMID 41150735, 2025). "Additionally, mice with cilia dysfunction, such as adenylate cyclase 3 (AC3) deletion, displayed leptin resistance and obesity, indicating cilia involvement in leptin signaling." (PMID 41251447, 2025). "One commonly proposed mechanism of obesity-related immune dysfunction is the underlying chronic inflammatory state of obesity, with increased levels of inflammatory cytokines including TNFα, IL6, and leptin." (PMID 40386706, 2025). "Various anthropometric parameters, obesity and diabetes factors, and BC clinical measures, as well as plasma levels of leptin, CD295, and ITLN1, were collected, as was information concerning the SNPs under study and DNA damage parameters for both the BC patients and the healthy controls." (PMID 41221514, 2025). "Resistance to both insulin and leptin, resulting from PTP1B overexpression, is a characteristic condition found in complex human diseases, such as T2DM and obesity, and can also be an important risk factor for developing metabolic syndrome, cancer and neurodegenerative disorders." (PMID 41302504, 2025). "As such, efforts to treat common obesity with leptin have failed." (PMID 41251447, 2025). "Leptin, an adipokine that is elevated in patients with obesity, influences VM in breast cancer." (PMID 41463012, 2025). "Elevated leptin levels also reduce reproduction in obesity through the effect of leptin on the kisspeptin-GnRH pathway while simultaneously compromising Sertoli cell function and Leydig cell testosterone synthesis, ultimately promoting oxidative stress and sperm dysfunction." (PMID 40292466, 2025). "Overall, this may suggest a regulatory role of leptin, where increased levels, as observed during obesity, tip the balance toward an exacerbation of the immune system and a loss of immune self-tolerance, potentially worsening MS progression." (PMID 40019662, 2025).